CDK4 (cyclin dependent kinase 4)
Diseases named in the same sentence as CDK4 in open-access papers (continued):
Sharing a sentence is not in itself a finding about the gene and the disease.
prostate carcinoma (continued). "Recent studies indicate that HDAC5 inhibitors boost RB1 expression and sensitise CDK4/6 inhibitors in prostate cancer cells." (PMID 40070134, 2025). "In this study, we aimed to estimate the contribution of these selected polymorphisms (CDK4 rs2069502, CDK6 rs2285332, CCND1 rs9344, p16INK4a rs11515, p15INK4b rs3217986, RB rs3092904) within the cyclin D-CDK4/6-INK4-RB pathway to prostate cancer risk." (PMID 40304827, 2025). "In this study, we show that miR-377 transfection causes a stop in the cell cycle of prostate cancer cell lines due to the decrease in the expression level of MYC mRNA and, thus, the reduction in the expression level of CDK4 mRNA." (PMID 38756697, 2024). "Our qPCR analysis revealed that treatment of Cur-B modulated the gene expression of cyclin D1, CDK4, and p21 in prostate cancer cells." (PMID 37448964, 2023). "CDK4/CDK6 inhibitors have also been shown to exert synergistic anticancer effects with BRD4 inhibitors in castration-resistant prostate cancer and NUT midline carcinoma." (PMID 38135679, 2023). "We are actively seeking to validate our published prostate cancer PDE data that showed efficacy of CDK4/6 inhibitors, through a pharmacodynamic neoadjuvant clinical study of CDK4/6 inhibitors in prostate cancer." (PMID 35406480, 2022). "Conversely, if the cyclin D and cdk4/6 levels are decreasing, it shows that the prostate cancer cell phenotype is going back to less malignant one." (PMID 34677582, 2021). "We have also found that knockdown of CDK4 in combination with HSP90 inhibition inhibited the level of HIF1α in PC3 prostate cancer cell line." (PMID 34686682, 2021). "Another study also revealed that G. lucidum triterpenoid induced mainly cell cycle arrest at the G1/G0 phase, which was due to the upregulation of p21 expression and the downregulation of CDK4 expression in prostate cancer cells." (PMID 33142749, 2020). "For example, prostate cancer Phase IB/II trials are ongoing for the CDK4/6 inhibitors ribociclib (ClinicalTrials.gov identifier: NCT02555189, NCT02494921) and palbociclib (NCT02905318, NCT02059213), and the CHEK1 inhibitor LY2606368 (NCT02203513)." (PMID 30616540, 2019). "For example, HOXC6 and DLX1 genes, which are biomarkers and key players of prostate cancer development as well as genes involved cell cycle (CDK4, CDC23, MYC) and androgen signaling (AR, GRHL2) are found." (PMID 31515496, 2019). "It has been demonstrated that cyclin D1 and CDK4 play central roles in the regulation of proliferation of prostate cancer." (PMID 31060254, 2019). "In our study, we analyzed the association of CDK4, TWIST1, and SNAI2 single gene expression with the prognosis of prostate cancer patients in the GSE21032 dataset taken from the SurvExpress database." (PMID 31060254, 2019). "Collectively, this study is the first to report that protein expression of the CDK4, twist, and slug is induced by GA in prostate cancer cells, and their aberrant expression together accurately predicted prostate cancer patient’s outcomes." (PMID 31060254, 2019). "In prostate cancer, artemisinin inhibits cell division by inducing G1 cell cycle arrest and inhibiting CDK4 gene expression." (PMID 28737711, 2017). "In prostate cancer cells, cytoplasmic cyclin D1/CDK4 complexes phosphorylate paxillin, a structural component of focal adhesions." (PMID 29066743, 2017). "Ki-67, cyclin D1 and CDK4 were over expressed in prostate cancer, concomitant with significant down regulation of p21 in prostate cancer." (PMID 28852180, 2017). "In vitro cell culture results revealed that BITC decreased DNA synthesis, as well as CDK2 and CDK4 activity in TRAMP-C2 mouse prostate cancer cells." (PMID 26907265, 2016). "Further studies are needed to determine the effect of increased AhR expression on CDK4 activity in advanced prostate cancer cells." (PMID 24755659, 2014). "In prostate cancer, it has been demonstrated that the expression of CDK4 was decreased after Med19 disruption." (PMID 23705783, 2013).
prostate carcinoma (continued). "It has been previously shown through in vitro studies that cyclin D1 can influence androgen-dependent prostate cancer cell proliferation through its dual ability to modulate both CDK4 and AR activity." (PMID 17375037, 2007). "In addition, decreased expression of Su(H) can significantly inhibit cell growth via suppression of its target genes CDK2, CDK4, CyclinD1, and Bcl-2, and upregulation of P21 and P27 to induce cell cycle arrest in prostate cancer cells." (PMID 40151788, 2025). "We evaluated CDK4 rs2069502, CDK6 rs2285332, CCND1 rs9344, p16INK4a rs11515, p15INK4b rs3217986, and RB rs3092904 polymorphisms using TaqMan® SNP Assays in a cohort comprising 532 prostate cancer patients and 567 control subjects." (PMID 40304827, 2025). "This truncated fumaramide handle maintainedrobust degradation of BRD4 and expanded the scope of neo-substratetargets, including CDK4/6, SMARCA2/4, and notably, the androgen receptor(AR) and its therapeutically challenging truncation variant AR-V7in androgen-independent prostate cancer cells." (PMID 40726802, 2025). "In prostate cancer, the roles of CDK4 and CDK6 remain less clear." (PMID 40304827, 2025). "We will also explore possible mechanisms of resistance to CDK4/6 inhibitors that may be particularly relevant in prostate cancer patients and the investigational agents that may be utilized to overcome these resistance pathways." (PMID 40075623, 2025). "The rationale for combining CDK4/6 inhibitors with radiation is in part based on data supporting the importance of cyclin D1 in radio-sensitizing prostate cancers and the possibility that CDK4/6 inhibition may potentiate the effects of radiation." (PMID 40075623, 2025). "In the following section, we will review the known mechanisms of resistance to CDK4/6 inhibition that may have particular relevance to prostate cancer patients and propose approaches to combating those mechanisms." (PMID 40075623, 2025). "Also, Real-time PCR analysis of prostate cancer cell lines transfected with miR-377 revealed that the expression level of CDK4 mRNA was lower than that of control cells (0.341 ± 0.0225 in PC-3 cells and 0.2915 ± 0.024 in DU145)." (PMID 38756697, 2024). "Similarly, a study on prostate cancer showed that Piezo1 downregulation inhibited the expression of Cyclin D1 and CDK4, hindering the assembly of the Cyclin D1-CDK4 complex and thus impeding cell cycle progression in prostate cancer cells." (PMID 38690080, 2024). "Therefore, in the molecular diagnosis of prostate cancer, we can also introduce changes in the levels of c-Myc, eIF4E and CDK4 to evaluate the progression of prostate cancer." (PMID 34863188, 2021). "Accordingly, RB1 overexpression is reported to confer sensitivity to CDK4/6 inhibition in prostate cancer, although its loss or deletion is not currently reported as a non-response biomarker." (PMID 32907621, 2020). "It was reported that miR-145 could induce the cell cycle arrest and inhibit cell proliferation by inhibiting the expression of CDK4 and c-Myc in prostate cancer cells and non-small cell lung cancer cells." (PMID 31582906, 2019). "Finally, there is increasing evidence the E2F-induced cyclin/CDK hyperactivity in prostate cancer is an ideal target for CDK4/6 inhibition." (PMID 28418845, 2017). "Androgen receptor dependent upregulation of D-type-cyclins leading to activation of the cyclin D1/CDK4/6 complex and proliferation in prostate cancer cells suggests that targeting this axis may be effective in castration resistant prostate cancer (CRPC)." (PMID 28418845, 2017).
prostate carcinoma (continued). "In comparison with quiescent status of prostate cancer cells, we noticed an accumulation in cyclin D1, CDK4, cyclin E and CDK2 together with the expected reappearance of phosphorylated pRb when the quiescent cancer cells were induced to re-enter the cell cycle." (PMID 26416244, 2015). "Finally, when prostate cancer cell lines were treated with the CDK4/6 inhibitor PD0332991, the cell lines responded to the treatment according to miR-193b expression/methylation status and cyclin D1 levels." (PMID 26129688, 2015). "Whether the AR-mediated cellular growth seen in prostate cancer cells as well as other dysregulated cellular functions such as PI3K/AKT pathway activity and DNA repair dysfunction render prostate cancers susceptible to CDK4/6 inhibition is an open question." (PMID 40075623, 2025). "Several reports have shown that Cdk4 hyperactivity is associated with the overexpression of cyclin D and several cancers showing elevated levels of cyclin D1 expression including breast (60% of patients), CRC (40% of patients), and prostate cancers (20% of patients)." (PMID 32847114, 2020). "Thus, inhibition of cyclin D1 and E and cdk2, cdk4 and cdk6 suggests that PM might inhibit proliferation by arresting prostate cancer cells in G1-phase." (PMID 25175770, 2014). "The relative mRNA expression levels of CDK4, CDK6, CCND1, p16INK4a, p15INK4b, and RB were assessed in 44 prostate cancer tissues and 31 BPH tissues using qRT-PCR." (PMID 40304827, 2025). "The absence of AR activity has been shown to lead to reduced levels of cyclin D3 and cyclin A, reduced CDK4 and CDK2 activity, the hypophosphorylation of Rb, and G1 arrest in prostate cancer cells." (PMID 40075623, 2025). "Lastly, PF-07220060, a selective CDK4 inhibitor that spares CDK6, is being assessed in combination with enzalutamide in patients with prostate cancer in a phase 1/2a study whose primary outcome is safety (NCT04557449)." (PMID 40075623, 2025). "Therefore, we hypothesized that polymorphisms of genes encoded cyclin-dependent kinase 4 and 6 (CDK4 and CDK6), cyclin D1 (CCND1), CDK inhibitors p16INK4a and p15INK4b, as well as the retinoblastoma protein (RB), could modulate prostate cancer risk and influence the corresponding mRNA levels." (PMID 40304827, 2025). "In this study, we found that MA inhibits the expression of CDK2, CDK4, and CDK6 and enhances that of p27, Rb and p-Rb to block G1/S transition in the cell cycle of prostate cancer cells." (PMID 39624845, 2024). "We observed a significant reduction in BCL-2 and CDK4 expression, along with an increase in Bax and PTEN, in prostate cancer cell lines upon MYC suppression." (PMID 38756697, 2024). "Herein we found that MA inhibits prostate cancer cell proliferation by decreasing CDK2, CDK4, and CDK6 expression and concurrently increasing p27, Rb, p-Rb expression." (PMID 39624845, 2024). "Mechanistic studies showed that Co-Sp reduced the expression of cyclin D1, cyclin E, CDK4, CDK2, MMP-9, MMP-1, and Bcl-2, and increased the expression of p21, cleaved caspase-9, cleaved caspase-3, cleaved PARP, and Bax in prostate cancer cells." (PMID 37313467, 2023). "Simvastatin and lovastatin suppressed expression of CDK1, CDK2, CDK3, CDK4, and CDK6 in prostate cancer cells with reduced cell viability due to induced apoptosis and cell cycle arrest." (PMID 36946734, 2023). "In MAT-LyLu cells, gossypol reduced the expression of cyclin D1, cyclin-dependent kinase 4 (CDK4), and phospho-retinoblastoma (p-Rb), which regulate the progression of the cell cycle in prostate cancer cells." (PMID 36559116, 2022). "Conversely, prostate cancer cells expressing high levels of miR-193b levels and low levels of CCND1 were resistant to the CDK4/6 inhibitor palbociclib." (PMID 34439268, 2021). "In contrast, the protein levels of c-Myc, CDK4, and CDK2 were increased by overexpression of Jun D in prostate cancer cells." (PMID 33669811, 2021).
prostate carcinoma (continued). "Other recent results have indicated that Jun D knockdown can reduce the protein levels of cell cycle regulators including c-Myc, CDK4, and CDK2 in prostate cancer cells." (PMID 33669811, 2021). "Fourth, GA-mediated the expression of one pro-proliferative cell cycle regulator (CDK4) and two EMT-TFs (TWIST1 and SNAI2) of prostate cancer cells can act as a marker of GA exposure." (PMID 31060254, 2019). "Collectively, these results indicated that there was low expression of CCND1, CDK4 and TWIST1; high expression of SNAI1, SNAI2, and CDH1 was correlated with good prognosis of prostate cancer patients." (PMID 31060254, 2019). "Hono also caused cell cycle arrest by decreasing the expression of cell cycle-related proteins, such as cyclin D1, CDK4 and CDK6 in PC-3 prostate cancer cells." (PMID 27074557, 2016). "Because cyclin D1 regulates the activity of CDK4/6, we treated PC cell lines with the CDK4/6 inhibitor PD0332991 at different concentrations and measured the effect on prostate cancer cell growth." (PMID 26129688, 2015). "Alterations of the gene profile of LAMB2 and CDKN2C/p18(Ink4c), a CDK4 inhibitor, have been reported on the transition from prostatic intraepithelial neoplasia (PIN) to prostate cancer." (PMID 20805891, 2010). "We also highlight alternative cell cycle targets, such as CDK2 and CDK7, as well as novel combination trials that remain under investigation, in which CDK4/6 is used to modulate the biology of the prostate cancer cell rather than effect a cytostatic change." (PMID 40075623, 2025). "CDK4/6i are also in clinical trials for prostate cancer, however these have not specifically assessed outcomes in the bone metastatic setting." (PMID 41091336, 2025). "As of this writing, there are no FDA-approved indications for the use of CDK4/6 inhibitors in prostate cancer patients." (PMID 40075623, 2025). "The results indicated that YTHDF1 does not bind to the mRNAs of CDK2 and CDK4 in prostate cancer cells." (PMID 40251202, 2025). "It has been reported that genistein may inhibit the proliferation of prostate cancer cells through regulating the expression of ER-akt, PSA, p21, Cyclin D1, CDK4, etc.." (PMID 36794010, 2023). "Formononetin can induce prostate cancer transformation through the ERK1/2 MAPK-Bax pathway, which can also inhibit the G1 cell cycle by inactivating Akt/cyclin D1/CDK4, making it exhibit inhibitory activity on human prostate cancer cells both in vivo and in vitro." (PMID 35594510, 2022). "CDK4, TWIST1, and SNAI2 three-genes were selected based on the significant expression profiles of these genes, and prognostic relevance of these genes for prostate cancer patients." (PMID 31060254, 2019). "Our data suggest concurrent targeting of BMI1 and CDK4/CDK6 might provide novel therapeutic opportunity for breast, colon, and prostate cancer." (PMID 31548560, 2019). "Thus, we identified the most significant model of three-gene signature (CDK4, TWIST1, and SNAI2) that was able to predict the survival of prostate cancer patients for the first time." (PMID 31060254, 2019). "Soy milk digestion extract (daizein, glycitein, genistein) might inhibit the proliferation of in vitro human prostate cancer cells by regulating the expression of ERβ, PSA, p21, Cyclin D1 and CDK4 in an estrogen receptor (ER)-dependent manner." (PMID 29844867, 2018). "Moreover, in prostate cancer, EZH2 can repress the expression of tumor suppressors such as DAB2IP, p16 (CDKN2A), CDK4, E-cadherin (CDH1), MSMB, Ras (KRAS), NF-κB (NFKB1), EMT regulator." (PMID 27835578, 2016). "We also noted that Ki67+ proliferating cells and the expression of cell proliferation-related proteins (CDK2, CDK4, and Cyclin A) were increased in the tumor tissues of HFD-fed mice injected with TRAMP-C2 prostate cancer cells and in the DP of HFD-fed TRAMP mice." (PMID 25912035, 2015).
prostate carcinoma (continued). "Given its robust modulation of several cellular pathways that are highly relevant to prostate cancer such as AR signaling and the cyclin D1/CDK4/RB axis, we tested whether SMIP004 exhibited anti-prostate cancer activity in murine xenograft models." (PMID 23902736, 2013). "VPA diminished cdk1 in all prostate cancer cell lines, whereas cdk2 and cdk4 were reduced in DU-145 and LNCaP, but not in PC-3 cells." (PMID 21867506, 2011). "However, in colon cancer cells, G1 arrest occurs via p21 upregulation and pRB phosphorylation without altering cyclin D/CDK4 levels, while prostate cancer models implicate GADD45A/JNK signaling." (PMID 40735485, 2025). "This lack of efficacy may be due to intrinsic resistance of prostate cancer cells to CDK4/6 inhibition, which may occur via a variety of mechanisms, which we will explore in the coming sections." (PMID 40075623, 2025). "However, the potential associations between other polymorphisms – such as CDK4 rs2069502, CDK6 rs2285332, p16INK4a rs11515, p15INK4b rs3217986, RB rs3092904 – and prostate cancer risk have not yet been elucidated." (PMID 40304827, 2025). "There are no active clinical trials of CDK4/6 inhibitors with MEK inhibitors in prostate cancer." (PMID 40075623, 2025). "Similarly, formononetin induced G1 arrest in PC-3 and DU-145 prostate cancer cells by downregulating cyclin D1, protein kinase B (AKT), and cyclin dependent kinase 4 (CDK4) in a concentration-dependent manner, and this phenomenon was observed to be more significant in PC-3 cells than DU-145 cells." (PMID 31052435, 2019). "Finally, heat map analysis showed that prostate cancer and BPH tissues may be distinguished on the basis of the expression of the genes such as FKBP4, FGF8, c-Myc in addition to cyclinD1, CDK4, Ki-67 and p21." (PMID 28852180, 2017). "These were 7 tests for h-caldesmon (for leiomyosarcoma), 3 CDK4 (for WDL/DDL), 2 DOG1 (for GIST), 2 beta-catenin (for fibromatosis), 1 each of CD34 (DFSP), desmin, myogenin (rhabdomyosarcoma (RMS)), p63 (sarcomatoid carcinoma), PSAP (prostatic carcinoma), and TLE1 (synovial sarcoma)." (PMID 25165418, 2014). "The only exception was the negative correlations of CDK4 and CDK6 (r = −0.5) with prostate cancer." (PMID 33668805, 2021).